CAV1 (caveolin 1)
Diseases named in the same sentence as CAV1 in open-access papers (continued):
Sharing a sentence is not in itself a finding about the gene and the disease.
colon carcinoma (continued). "In this respect, it is worth noting that the regulation of β-catenin-dependent transcription by caveolin-1 is likely to be relevant in human cancers, especially those where β-catenin-dependent transcription is altered, such as colon cancer." (PMID 18400052, 2008). "Caveolin-1 expression is down-regulated both in colon tumour mucosa and stroma when compared to samples of normal tissue from the same patients." (PMID 18400052, 2008). "In colon cancer, ligand activation of PPARγ-mediated differentiation of certain colon cancer cells results in the upregulation of tumour suppressor genes caveolin 1 and 2 and repression of cyclin D1 expression." (PMID 15583697, 2005). "Similarly, a previous study indicated that suppressing Cav-1 gene expression reduces the production and secretion of cathepsin B precursors in colon cancer cells." (PMID 40135201, 2025). "Yu and their colleagues indicated that the IFITM1 could facilitate colon cancer metastasis by regulating CAV-1." (PMID 37063301, 2023). "CAV1 expression was also found to be high in methotrexate-resistant HT29 colon-cancer cells, and its downregulation by siRNA concomitant with overexpression of E-cadherin significantly reduced cell viability suggesting that these are potential targets for combination therapy in colon cancer." (PMID 35158857, 2022). "An elevated level of CAV1 expression may contribute to colorectal tumor progression by enhancing aerobic glycolysis in colon cancer cells." (PMID 36146640, 2022). "In addition, treatment of colon cancer cells with histone deacetylase inhibitors, such as trichostatin A, increases CAV1 expression and prevents cell proliferation." (PMID 32458269, 2020). "CAV-1 moderates lipid trafficking and is known to be up-regulated in drug resistant cancer cell lines and in colon cancer, histone modifications bring about the genetic drift in CAV-1 gene regulation instead of DNA methylation, which agrees with the observations by Western blot analysis." (PMID 31889941, 2019). "Also, we provide direct evidence in DNA immunoprecipitation assays using methylation-specific antibodies that the CAV1 promoter region is demethylated upon exposure of colon cancer cells to Methotrexate or Etoposide." (PMID 29340103, 2017). "Finally, elevated CAV1 expression in colon cancer cells following exposure in vitro to sub-cytotoxic drug concentrations increased their metastatic potential in vivo." (PMID 29340103, 2017). "In both colon cancer cell lines, treatment with the anti-neoplastic drugs decreased significantly methylation of the CAV1 promoter region, which likely explains, at least in part, the increase in CAV1 mRNA and protein levels observed following drug exposure." (PMID 29340103, 2017). "In HT29 colon cancer cells, resistance to the anti-neoplastic drug Methotrexate correlates with higher levels of CAV1 in comparison to untreated cells and silencing of CAV1 expression by RNA interference decreases the MDR phenotype and sensitizes cells to Methotrexate treatment." (PMID 29340103, 2017). "Moreover, in human colon cancer cells, caveolin-1 affects the expression and localization of cathepsin B and pro-urokinase and their receptors, thereby mediating cell-surface proteolytic events associated with invasion." (PMID 25822177, 2015). "Survival analysis of the Cav-1 expression in colon cancer (120 samples) and rectal cancer (131 samples) patients has also identified that Cav-1 expression significantly correlates with distant metastasis in colon cancer and decreased disease-free survival (P=0.005) in rectal cancer." (PMID 25202343, 2014). "Studies have shown that caveolin-1 is over-expressed in colon cancer tissues, as compared to normal colonic mucosa, and colon cancer cells, suggesting that caveolin-1 may have pro-tumorigenic properties in this type of cancer." (PMID 22745744, 2012). "Therefore, caveolin-1 acts as an anti-apoptotic molecule in colon cancer cells by inhibiting Bax-dependent cell death." (PMID 22745744, 2012).
colon carcinoma (continued). "Thus, caveolin-1 acts as an anti-apoptotic protein in colon cancer cells by binding to Ku70 and inhibiting Bax-dependent cell death." (PMID 22745744, 2012). "However, whether and how caveolin-1 modulates apoptosis of colon cancer cells remains to be determined." (PMID 22745744, 2012). "Furthermore, caveolin-1 levels were found to be extremely low in a number of different colon carcinoma cell lines and re-expression of caveolin-1 was sufficient to block tumour formation of colon carcinoma cells in nude mice." (PMID 18400052, 2008). "CAV1 expression is upregulated by rosiglitazone, a peroxisome proliferator-activated receptor-gamma (PPAR-γ) ligand in colon-cancer cells." (PMID 35158857, 2022). "This warrants further investigation to determine if CAV-1 and MMP-9 are biomarkers of early colon cancer or an indicator of abnormal growth in colon mucosa." (PMID 31889941, 2019). "We intended to analyse our patient population (Asian/Pakistani) and establish CAV-1 and MMP-9 significance in colon cancer." (PMID 31889941, 2019). "GSTO1 knock-down by the inhibitor C1-27 in colon cancer cell line HCT116 resulted in down-regulation of Dickkopf-related protein 1 (DKK1), thombospondin 1 (THBSS1) and CAV-1." (PMID 31889941, 2019). "To that end, we treated the colon cancer cell lines HT29(US) and DLD-1 with either Methotrexate or Etoposide for 12 and 24 h, and evaluated CAV1 mRNA levels by qPCR analysis." (PMID 29340103, 2017). "High levels of CAV1 were observed in a number of MDR cancer cell lines, such as adriamycin-resistant MCF-7 breast adenocarcinoma cells and colchicine-resistant HT-29 colon carcinoma cells." (PMID 26843476, 2016). "Specifically, in colon cancer cells selected for resistance to methotrexate (HT29-5M21 or M12) or with higher metastatic potential (Lovo E2 versus LovoE5), caveolin-1 levels are elevated with respect to those detected in the wild-type cells." (PMID 18400052, 2008). "Caveolin-1 and COX-2 showed an inverse relation in colon cancer cell lines." (PMID 35409055, 2022). "Colon cancer cells with over-expression of caveolin-1 (HCT116) also have abundant mitochondrial localization, and in low-expression cells (HT29), over-expression of caveolin-1 leads to its enrichment in mitochondria and reduced apoptosis." (PMID 35064107, 2022). "Hypermethylation in Cav‐1 promoter region was reported in patients with colorectal cancer, whereas 5‐AZA could inhibit colon cancer cell growth through the Cav‐1 signal pathways." (PMID 32508059, 2020). "Also, activation of PPARγ correlates with an increase in CAV1 mRNA in breast and colon cancer cells, and RANKL up-regulates CAV1 during osteoclastogenesis." (PMID 29340103, 2017). "Hence, Methotrexate- and Etoposide-enhanced cell migration depends on CAV1 re-expression in HT29(US) and DLD-1 colon cancer cells." (PMID 29340103, 2017). "Colon cancer cells (HCT116) that overexpress CAV1 also had its abundant localisation in the mitochondria and, in the low expressing cells (HT29), overexpression of CAV1 led to its enrichment in the mitochondria and reduced apoptosis." (PMID 27852311, 2016). "If knockdown of caveolin-1 protein expression potentiates apoptosis in colon cancer cells by enhancing the release of Bax from Ku70, one would not expect potentiation of apoptosis by knockdown of caveolin-1 in HCT116 cells lacking Bax expression." (PMID 22745744, 2012). "Thus, we decided to search for other differentially expressed genes (CAV1, E-cadherin, ENO2 and PKCα) that had been previously related with resistance or with colon cancer and to evaluate their relative contribution in our cell system." (PMID 18694510, 2008). "In this study, we show that raft-dependent uptake of AMF/PGI is specific for gp78/AMFR-positive/Cav1-negative metastatic colon cancer cells, does not target normal immune cells and occurs in vivo in subcutaneous K1735-M1 and B16-F1 melanoma tumor models." (PMID 18974847, 2008).
colon carcinoma (continued). "However, the regulatory mechanism of CAV1 in colon cancer in terms of membrane tension is not well understood." (PMID 36146640, 2022). "Since HT-29 human colon cancer cells are not sensitive to EGF stimulation due to the lack of a canonical peroxisome proliferator-activated receptor-gamma response element (PPRE), we speculated that EGF may regulate caveolin-1 expression through peroxisome proliferator-activated receptor-gamma." (PMID 19816600, 2009).
Insulin resistance (52 papers, 2008 to 2025). Increased resistance towards insulin, that is, diminished effectiveness of insulin in reducing blood glucose levels. "Caveolin-1 is essential for improving insulin sensitivity, and studies have shown that Cav-1-deficient mice exhibit insulin resistance and defective insulin receptor protein expression." (PMID 41280311, 2025). "In conclusion, our study highlights the pivotal role of cPLA2 in regulating Cav-1 function and insulin signaling in AD, offering insights into potential therapeutic targets for mitigating insulin resistance associated with the disease." (PMID 41280311, 2025). "Recently, certain genetic strains of CAV-1 have been associated with insulin resistance and hypertriglyceridemia." (PMID 38268038, 2024). "It is understood that overexpression of Cav-1 is linked to reduced acetylcholine-induced NO generation and vasodilation in patients with insulin resistance and type 2 diabetes." (PMID 33995826, 2021). "In light of this, the aim of this study was to evaluate the alterations in the expression of a panel of genes, including CAV1, implicated in the modulation of weight change and insulin resistance." (PMID 32125224, 2020). "CAV-1-deficient mice showed a lean body phenotype, insulin resistance, and hypertriglyceridemia with adipocyte abnormalities." (PMID 33148167, 2020). "In humans, homozygous mutation in the CAV1 gene causes CGL3, where affected patients have postprandial hyperinsulinemia, severe insulin resistance, hypertriglyceridemia, and lipodystrophy." (PMID 32082483, 2020). "Reduced phosphorylation of Y14 caveolin-1 has been associated with the insulin resistance state in patients with polycystic ovary syndrome." (PMID 31658625, 2019). "Caveolin 1 gene (CAV1) has been associated with insulin resistance, metabolic syndrome and hypertension in humans." (PMID 29662258, 2017). "The loss of CAV1 leads to insulin resistance, and several of its genetic variants are associated with type 2 diabetes and lipid disorders." (PMID 27852311, 2016). "Loss of murine Cav1 causes vascular defects and insulin resistance and similar pathologies are seen in humans harboring Cav1 null alleles." (PMID 22493697, 2012). "Mice with a deleted Cav1 gene encoding caveolin-1 develop adipocyte abnormalities and insulin resistance." (PMID 18237401, 2008). "The CAV1 gene variant rs926198 is related with metabolic syndrome in different cohorts such as Caucasian and Hispanic, and other genetic variants have been associated with insulin resistance, too." (PMID 35059043, 2022). "It is interesting to note that any metabolic disorders such as obesity, insulin resistance, diabetes, and diabesity may cause a change in the structural integrity of caveolae or Cav-1 concentration, leading to vascular dysfunction." (PMID 33995826, 2021). "Cav-1 deficient mice develop post-prandial hyperglycaemia and insulin resistance." (PMID 26110317, 2015). "Additionally, genetic variations in Cav-1 have been implicated in systemic insulin resistance." (PMID 40358155, 2025). "This regulatory network is further supported by in vivo studies demonstrating that Cav-1 knockout mice exhibit pronounced insulin resistance, whereas Cav-1 upregulation enhances insulin signaling and insulin-induced glucose uptake." (PMID 40243482, 2025). "Increased Cav1 expression is observed in patients with insulin resistance and type 2 diabetes, while Cav1 knockout mice exhibit increased systemic NO and dilated ventricles." (PMID 39456198, 2024). "Caveolin-1 knockout mice were reported to exhibit fasting hyperinsulinemia, insulin resistance, and glucose intolerance." (PMID 38999937, 2024). "It has been reported previously that Cav-1 knockout mice display insulin resistance and when fed a HFD, Cav-1 knockout mice develop postprandial hyperinsulinemia." (PMID 35250626, 2022). "In contrast, gain of miR-103a function in either liver or adipocytes was sufficient to induce insulin resistance by downregulating caveolin-1." (PMID 36613525, 2022).
Insulin resistance (continued). "MiR-103a-3p is found in adipose tissue cells, regulating mRNA expression, and causing insulin resistance by altering GLUT4, IRS-1 and caveolin-1 (cav-1)." (PMID 36432399, 2022). "This miR-103-3p overexpression in liver or fat results in Insulin Resistance (IR) by down-regulation of caveolin-1." (PMID 36296907, 2022). "This suggested that insulin resistance was more severe in caveolin-1 silenced mice than mice in the control group." (PMID 34917687, 2021). "In the molecular biology researches of insulin resistance and metabolism, caveolin-1 has been studied since early 1990s." (PMID 34917687, 2021). "Among them, Caveolin-1 (CAV1) has been pointed out as one of the genes upregulated in fat tissue of rats in response to a high-fat diet and shown to be involved in insulin resistance." (PMID 32125224, 2020). "Previous studies demonstrated that CAV1 is critical for insulin receptor-mediated signaling, insulin secretion, and potentially the development of insulin resistance." (PMID 32082483, 2020). "Cav‐1 knockout and Cav‐1‐targeted microRNA contribute to the development of insulin resistance by blocking insulin‐elicited tyrosine phosphorylation and activation of IRβ." (PMID 28514055, 2017). "For instance, mice with induced deficiency in Cav1 encoding the cell surface protein caveolin-1 (MIM 601047) showed depleted and abnormal adipocytes with insulin resistance and severe hypertriglyceridemia." (PMID 18237401, 2008). "CAV1 is a cell surface protein shownto play a key role in insulin resistance." (PMID 36837510, 2023). "Similarly, miR-103a-2, which is upregulated in NAFLD, induces insulin resistance by targeting caveolin-1 (Cav1), a critical regulator of the insulin receptor stability and insulin action." (PMID 36613525, 2022). "Even with the atrophy of adipose tissue, CAV-1 null mice showed insulin resistance in our study." (PMID 34917687, 2021). "Caveolin-1 knockout mice develop remarkable insulin resistance, while upregulation of caveolin-1 could enhance insulin signal transduction and therefore improve glucose uptake after insulin stimulation." (PMID 34917687, 2021). "In the current study, we found that caveolin-1 could play a vital role in alleviating insulin resistance during insulin treatment by activating AKT phosphorylation." (PMID 34917687, 2021). "Our findings identify a potential cav-1 dependent mechanism through which OSA may contribute to insulin-resistance as well as a vasoconstrictive profile." (PMID 30237409, 2018). "Cav‐1 knockout mice exhibit neurodegeneration with premature aging, reduced capacity of liver regeneration, fat atrophy, and pathological hypertrophy of heart and insulin resistance." (PMID 28514055, 2017). "Previous reports showed up-regulation of mRNA Cav-1 expression levels in visceral and subcutaneous adipose tissue of obese patients and highlighted the role of caveolins in energy and metabolic homeostasis as well as in body weight and insulin resistance." (PMID 26230734, 2015). "Furthermore, mice null for caveolin-3 and caveolin-1 display insulin resistance, glucose intolerance and decreased insulin-induced glucose uptake; re-expression of these proteins reverses these conditions." (PMID 25914646, 2015). "It was found in the animal experiments that ECD could reduce blood glucose, regulate lipid metabolism, and reduce the expression of IR, IRS-1, and Cav-1, so as to improve insulin resistance." (PMID 26504476, 2015). "Cav1 appears to have a significant role in murine adipocyte metabolism, and disruption of the gene leads to severe hypertriglyceridemia, insulin resistance and adipocyte abnormalities, which are all features that are consistent with human partial lipodystrophy." (PMID 18237401, 2008). "Importantly, Cav-1 knockout mice develop insulin resistance." (PMID 41280311, 2025).
Insulin resistance (continued). "In Cav-1 knockout mice, metabolic dysfunctions are intensified, indicating that genetic variations in Cav-1 may act as biomarkers for the early identification and management of insulin resistance and metabolic disorders." (PMID 40358155, 2025). "Although previous studies have reported the effects of TNF-α on insulin resistance and the destabilization of insulin receptor–CAV1 interactions, the association between this cytokine and CAV1 expression in normoglycemic obese individuals has not been studied before." (PMID 37048092, 2023). "Thus, we hypothesized that insulin treatment would upregulate Cav-1 expression in adipose tissue to alleviate insulin resistance." (PMID 34917687, 2021). "Thus, the lower expression of caveolin-1 could severe insulin resistance by affecting lipid metabolism." (PMID 34917687, 2021). "Cav-1 within the endothelium may be crucial in defining insulin uptake into peripheral skeletal muscle where over 80% of glucose uptake occurs and is a potential site for development of insulin resistance." (PMID 31534971, 2019). "Cav1/PKCzeta coupling antagonizes the activation of PI3K on Akt, leading to eNOS dysfunction, insulin resistance, and endothelial cell damage." (PMID 37289375, 2024). "Because of the key role of CAV-1 in pancreatic beta cells, it is well established that CAV-1 is involved in energy metabolism disorders such as insulin resistance and hypertriglyceridemia." (PMID 38268038, 2024). "Numerous genes are candidates for severe insulin resistance, such as INSR, BSCL2, AGPAT2, CAV1, and PTRF." (PMID 33995269, 2021). "In addition, as other studies have shown that insulin receptor expression and signaling is dependent on CAV1, increased expression of CAV1 in diabetic patients and mouse models may indicate an attempt to improve signaling under conditions of increased insulin resistance." (PMID 24608114, 2014). "Recent studies have confirmed that short-term exposure to high glucose significantly decreased the binding affinity of insulin to caveolin-1 and INSR in mature adipocytes, which might contribute to the development of insulin resistance in early T2DM." (PMID 31658625, 2019). "Nonetheless, basal glucose metabolism appears largely unaltered in hearts lacking either caveolin-3 or caveolin-1, and thus also devoid of caveolae, although skeletal muscle insulin-resistance arises in both models." (PMID 29202762, 2017). "They observed a disruption in CAV1 localization in the plasma membrane of adipocytes, complete abolishment of the insulin-stimulated P-Y14 residues of CAV1, and a decrease in GLUT4 translocation to the plasma membrane suggesting CAV1 relevance in hypoxia-induced insulin resistance." (PMID 32082483, 2020). "Our data-driven approach also revealed the central role of CAV1 in adipose tissue by elucidating its connection to a large number of CVD and T2D GWAS genes and to genes involved in focal adhesion and inflammation, which could drive adipocyte insulin resistance." (PMID 28957322, 2017).